SNORD32B (small nucleolar RNA, C/D box 32B)
Synonyms: U32B
Gene: Small nucleolar RNA gene on chromosome 6 (29,582,249 to 29,582,332, forward strand). Ensembl gene ENSG00000201330.
Gene Ontology:
Biological process: RNA processing
Cellular component: nucleolus
Homologues: Orthologues: chimpanzee SNORD33 (99% identical), macaque SNORD33 (96% identical), pig SNORD33 (89% identical), dog SNORD33 (88% identical), rabbit SNORD33 (85% identical), rat LOC120100339 (82% identical), mouse Snord32a (81% identical), zebrafish SNORD33 (62% identical), tropical clawed frog SNORD33 (58% identical), zebrafish SNORD33 (58% identical), tropical clawed frog SNORD33 (55% identical). Paralogues in human: SNORD32A (89% identical), SNORD33 (64% identical), SNORD33 (46% identical).